CEACAM5 (CEA cell adhesion molecule 5)
Diseases named in the same sentence as CEACAM5 in open-access papers (continued):
Sharing a sentence is not in itself a finding about the gene and the disease.
small cell lung carcinoma (9 papers, 1993 to 2021). Small cell lung cancer (SCLC) is a highly aggressive malignant neoplasm, accounting for 10-15% of lung cancer cases, characterized byrapid growth, and early metastasis. "The highest expression of CEACAM5 was in small-cell lung cancer specimens (5.5 ± 0.7), followed by large-cell neuroendocrine tumors (4.75 ± 3.18)." (PMID 17201906, 2007). "In particular, the classical serum marker CEACAM5 (CEA) is highly expressed in cancers including colorectal, gastric, pancreatic, and small cell lung cancer." (PMID 22162753, 2011).
gastric adenocarcinoma (8 papers, 2006 to 2025). "Consistently, CLDN4 and CEACAM5 mRNA levels are significantly higher in gastric adenocarcinomas compared to normal gastric samples from the large TCGA and GTEx cohorts, with CLDN4 showing higher expression levels than CEACAM5 in normal tissues." (PMID 40868067, 2025).
COVID-19 (7 papers, 2020 to 2025). A disease caused by infection with severe acute respiratory syndrome coronavirus 2. "We previously reported the clinical and molecular evidences supporting that SARS-Cov-2 infected the gastrointestinal (GI) tract and found a reduction of CEACAM5 in COVID-19 patients’ feces which associated with gut dysbiosis." (PMID 38686388, 2024). "And further studies are needed to explore the protective role of CEACAM5 in intestinal barrier injury especially in severe COVID-19 patients." (PMID 38686388, 2024). "Through fecal multi-omics analysis, we found a decrease in CEACAM5 levels in COVID-19 patients." (PMID 38686388, 2024). "We previously observed the decreased expression of host CEACAM5 protein in COVID-19 patients feces." (PMID 38686388, 2024). "To further validate the reduced CEACAM5 expression in feces of COVID-19 patients and explore its biological functions, mice models were established through intraperitoneally injecting recombinant viral spike-Fc containing RBD to mimic the intestinal inflammation as we previously reported." (PMID 38686388, 2024). "Here we discussed the underlying working mechanisms of CEACAM5 in intestinal barrier dysfunction induced by SARS-Cov-2 spike, which may provide promising therapeutic targets for alleviating GI symptoms in COVID-19 patients and further enhance the treatment of SARS-Cov-2 infection." (PMID 38686388, 2024). "In COVID-19, we also found that CEACAM8 is highly expressed in the developing neutrophils/neutrophil progenitors, while CEACAM5 and CEACAM6 are highly expressed in type II pneumocyte." (PMID 34217339, 2021). "This study illuminated the molecular mechanism of CEACAM5 in intestinal barrier dysfunction induced by SARS-Cov-2 spike, providing potential therapeutic strategies to alleviate intestinal barrier damage in severe COVID-19 patients." (PMID 38686388, 2024).
breast tumor (6 papers, 1981 to 2024). "To analyze the distribution of CEACAM5 expression in different subtypes of breast tumors, we examined a sample of frozen biopsies of which some previously have been utilized for testing CEACAM6-expression." (PMID 33196697, 2020). "A total of 110 breast tumors were subjected to immunohistochemical assessment by use of CEACAM5-specific mAbs CB30 and COL-1, CEACAM6 cross-reacting 1105 and CEACAM6-antibody 9A6." (PMID 33196697, 2020). "Tissues from patients with metastatic breast cancer confirmed elevated levels of CEACAM5 in lung metastases relative to breast tumors, and an inverse correlation between CEACAM5 and the mesenchymal marker vimentin was demonstrated." (PMID 29736411, 2018). "Co-staining for CEACAM5 and vimentin revealed higher levels of CEACAM5 in the lung metastasis relative to matched breast tumor, and the reverse staining pattern was observed for vimentin." (PMID 29736411, 2018). "Tissues samples from patients confirmed that CEACAM5 levels were elevated in metastatic lung tumors relative to primary breast tumors." (PMID 29736411, 2018). "Based on these results as well as experimental data performed on CEACAM5-expressing cell lines, we devise a hypothesis of a subtype-dependent role of CEACAM5 in breast tumor dissemination." (PMID 33196697, 2020). "Interestingly, CEACAM5 protein levels were higher in PDX MFP tumors established from the patient’s dermal metastasis (PIM001-M) compared with the PDX MFP tumors established from her primary breast tumor (PIM001-P)." (PMID 29736411, 2018). "Here, a functional genomic screen, performed in vivo using a PDX model derived from the primary breast tumor of a patient with metastatic TNBC, identified CEACAM5 as a metastatic driver, and functional studies demonstrated a role for CEACAM5 in late-stage metastasis." (PMID 29736411, 2018). "After comparing expression patterns in sets of primary breast tumors with corresponding lymph node metastases using commercially available TMAs, we hypothesized that CEACAM5-negative cancer cells may participate in tumor dissemination." (PMID 33196697, 2020).
gastric tumors (6 papers, 1984 to 2025). "CEA or CEACAM5 is a tumor antigen expressed preferentially by colorectal or gastric tumors." (PMID 35740244, 2022).
adenoma (5 papers, 2019 to 2025). A neoplasm arising from the epithelium. "In this study, CEACAM5 is the only DEG upregulated in the adenoma-normal and cancer-adenoma comparisons." (PMID 31211760, 2019).
asthma (5 papers, 2012 to 2025). "CEACAM5 is an IL-13-regulated epithelial gene that is upregulated in severe asthma and associated with increased asthma exacerbations." (PMID 38806494, 2024). "We identified 8 key genes (LOC100132287, CEACAM5, PRR4, CPA3, POSTN, LYPD2, TCN1, and SCGB3A1) associated with asthma by combining the LASSO regression model and the SVM-RFE method." (PMID 39963184, 2025). "Of the five modules upregulated in asthma cases, the strongest was a network (M6) with CEACAM5 as the hub gene (log2FC = 0.32, q = 9.62 × 10−16)." (PMID 38806494, 2024). "CEACAM5 is also one of the most highlyranked hub genes in the bronchial epithelium of patients with asthma." (PMID 35474304, 2022). "The association of the five genes CEACAM5, POSTN, TCN1, SCGB3A1, and CPA3 with asthma has been extensively identified and validated, and these are the most highly upregulated genes in patients with asthma, and CEACAM5 is associated with resting mast cells and eosinophils." (PMID 39963184, 2025). "We further used a one-to-one format for comparison and validated with the GSE63142 dataset The genes CEACAM5, PRR4, CPA3, POSTN, TCN1, CST1 (Cystatin-SN), CLCA1, TPSAB1 and NOS2 (Nitric oxide synthase 2) were highly expressed in patients with asthma." (PMID 39963184, 2025). "The strongest evidence is seen in the two most differentially expressed modules M6 and M2, which have Th2-related hub genes (CEACAM5 and CPA3, respectively); both are upregulated in the asthma cases." (PMID 38806494, 2024). "A signature containing CEACAM5 together with CD14 and TLR2 representing a response to bacterial infection has been described from an analysis of epithelial brushings and T‐cell transcriptomics from severe asthma patients." (PMID 35474304, 2022). "In bronchial biopsies, CEACAM5 was the only one of two upregulated differentially‐expressed genes in the biopsies of severe asthma compared to nonsevere asthma." (PMID 35474304, 2022).
Crohn disease (5 papers, 2009 to 2022). A gastrointestinal disorder characterized by chronic inflammation involving all layers of the intestinal wall, noncaseating granulomas affecting the intestinal wall and regional lymph nodes, and transmural fibrosis. "The association between LF82 and Crohn disease is linked to up-regulation of CEACAM5 and CEACAM6 by intestinal epithelial cells, which is induced by LF82 through TNF-α secretion." (PMID 19709415, 2009). "While no other CEACAM family members exhibited altered splicing profiles, we did observe elevated gene expression of CEACAM5, known to be a marker of Crohn’s disease, in the spliceopathy samples." (PMID 34301333, 2021). "Biopsies from patients with pediatric Crohn’s disease (CD) and adult ulcerative colitis (UC, active/inactive disease) showed a significant increase in CEACAM3, -5, -6 expression, while CEACAM5 expression was reduced in adult CD patients (active/inactive disease)." (PMID 34394073, 2021).
endometrial cancer (5 papers, 2021 to 2025). Primary or metastatic malignant neoplasm involving the endometrium (mucous membrane that lines the endometrial cavity). "The CEACAM5 gene, a member of the CEACAM gene family, encodes CEA (carcinoembryonic antigen) and represents a widely used tumor marker in various cancer types such as colorectal, gastric, pancreatic, lung, ovarian and endometrial cancer." (PMID 38730739, 2024).
gastritis (4 papers, 2012 to 2025). Inflammation of the stomach. "In relation to HopQ specifically, CEACAM1, CEACAM5 and CEACAM6 are all upregulated in gastritis caused by chronic H. pylori infection, again suggesting a mechanism for H. pylori promoting its own persistence in an inflammatory environment." (PMID 38615147, 2024).
inflammatory bowel disease (4 papers, 2020 to 2024). A spectrum of small and large bowel inflammatory diseases of unknown etiology. "CEACAM5 expressed on intestinal epithelial cells (IECs) can bind with CD8α on CD8+ suppressor T cells, leading to the inhibition of CD8+ suppressor T cell activation and the increasing proliferation of CD4+ T cells in inflammatory bowel disease (IBD) patients." (PMID 38686388, 2024).
metastatic carcinoma (3 papers, 2007 to 2020). A carcinoma which has spread from the original site of growth to another anatomic site. "In contrast to the findings in metastatic cancer, CEACAM5 consistently remained below the outlier threshold for all five non-metastatic solid cancer diagnoses and two blood cancers in this study." (PMID 33004987, 2020).
schizophrenia (3 papers, 2011 to 2015). A major psychotic disorder characterized by abnormalities in the perception or expression of reality. "These genes included SBNO2, CEACAM5, AKAP1, UBC, ACTB, UBB, and FOS for schizophrenia; SEC24C, PGLYRP1, ARHGAP4, RPL22, SLC6A11, and SYK for bipolar disorder; and SRRT, PARK2, LILRA4, STK17A, IGFBP2, and NF1 for major depression." (PMID 22373040, 2011).
viral infections (3 papers, 2013 to 2024). "The up-regulation via viruses and the effects of the inflammatory cytokine IFNγ imply a more general role for CEACAM1 and CEACAM5 in the inflammatory response to infection, and also in the spatial and temporal association between bacterial and viral infections." (PMID 23941132, 2013). "While for CEACAM1, CEACAM5 and CEACAM6 an up-regulation by IFNγ and viral infections has been described in epithelial cells, to our knowledge this is the first report that also type I interferons enhance CEACAM1 expression." (PMID 23941132, 2013). "Since viral infections trigger interferon-induced gene expression in epithelial cells to orchestrate immune responses, we also stained for co-stimulatory molecules CD80 and CD86, or immune-activating molecules CEACAM5 and CEACAM6." (PMID 36827975, 2023).
bipolar disorder (2 papers, 2011 to 2020). A disorder of the brain that causes unusual shifts in mood, energy, activity levels and the ability to carry out day-to-day tasks. "Although it is unclear whether alterations in CEA serum levels cause or arise due to bipolar disorder, reducing the CEACAM5 serum levels might be a promising approach." (PMID 32398742, 2020). "Among the drugs connected to the remaining PND-related genes, we highlight those that act upon IL13 for autism and CEACAM5 for bipolar disorder." (PMID 32398742, 2020).
aphthous ulcers (1 paper, 2025). "A key observation herein is the profound increase in expression of CEACAM5/6/7 mRNA in aphthous ulcers." (PMID 40386941, 2025).
cutaneous melanoma of the skin (1 paper, 2021). "The signature genes CEACAM5, ITGA10 and MMP13 had the highest proportion of mutations among all 467 patients with cutaneous melanoma of the skin." (PMID 34675134, 2021).
duodenal cancer (1 paper, 2019). "Among the DEGs identified, SPP1 and CEACAM5 have potential as serum biomarkers for duodenal cancer in FAP." (PMID 31211760, 2019).
lymph node tumor (1 paper, 2024). "Interestingly, CEACAM5 and CEACAM6 were absent in metastatic lymph node tumor tissue, compared to a matched primary tumor sample." (PMID 38502695, 2024).
mucinous colorectal adenocarcinoma (1 paper, 2020). "In addition, CEACAM5 was selected because it appears to be expressed in all primary tumors and generally at high levels and MUC2 because mucinous colorectal adenocarcinoma has a better prognosis than adenocarcinoma in general." (PMID 32049988, 2020).
prostate tumor (1 paper, 2007). "Eighteen stage-II, 15 stage-III, and 4 stage-IV prostate tumor cores were stained for CEACAM5 and CEACAM6." (PMID 17201906, 2007).
pterygium (1 paper, 2009). A wedge-shaped fibrovascular lesion arising from the bulbar conjunctiva and extending to the cornea. "Our results show that protein expression levels for keratin 6, CEACAM5, CD24, MSMB and MUC5AC were increased, whereas NR4A2 and IGFBP3 were reduced in pterygium, consistent with the transcript changes detected by the microarray analysis." (PMID 19272163, 2009). "Genes up-regulated in pterygium include fibronectin (FN1), CEACAM5 (CEA), CD24, SPARC, MSMB and TFF1." (PMID 19272163, 2009). "CEACAM5 (CEA), a common cancer marker, was up-regulated 3.8-fold in pterygium." (PMID 19272163, 2009).
tumor (2,313 papers, 1976 to 2026). "CEACAM5 (Carcinoembryonic Antigen-Related Cell Adhesion Molecule 5) is a marker of tumor progression and metastasis, implicated in cell adhesion and immune modulation (Qiu et." (PMID 40226632, 2025). "Immunohistochemical (IHC) analysis of tumor samples from 87 patients further revealed that CEACAM5 expression was significantly associated with tumor stage, lymphatic invasion, and histological grade." (PMID 41266534, 2025). "The study identifies hypoxia-induced exosomal CEACAM5 as a key driver of pancreatic neuroendocrine tumor (pNET) metastasis by promoting tumor-associated macrophage (TAM) M2 polarization and enhancing MMP9 secretion." (PMID 40303340, 2025). "Loss of pancreatic secretion-related genes along with alterations in ICAM1 and CEACAM5, contribute to the loss of normal exocrine function and promote tumor microenvironment remodeling." (PMID 40226632, 2025). "CEACAM5 (Carcinoembryonic Antigen-Related Cell Adhesion Molecule 5) is associated with cell adhesion and has been associated with tumor marker in various cancers." (PMID 40226632, 2025). "The CEACAM5 gene encodes the tumor marker carcinoembryonic antigen (CEA), and CEACAM5 is commonly overexpressed in PDAC and associated with epithelial–mesenchymal transition and poor prognosis." (PMID 39410042, 2024). "Another interesting aspect related to the targeting of CEACAM5/6 by CAR T-cells is the potential effects of this therapy on tumor-associated neutrophils, as these cells express high levels of CEACAM6." (PMID 38279989, 2024). "Further studies will evaluate if core-1 and/or extended core-1 O-glycans recognized by NEO-201 are attached to other specific tumor-associated proteins (beyond CEACAM5 and CEACAM6) expressed by the different types of tumors targeted by NEO-201." (PMID 36291783, 2022). "Here, we assessed a novel monoclonal antibody for its ability to direct ADCC activity of NK cells against cancer cells expressing an apparent tumor-associated variant of CEACAM-5 and CEACAM-6." (PMID 32637350, 2020). "Detached tumor cells can survive the integrin-mediated anoikis by direct interaction of cell-bound CEACAM5 with Death Receptor 5, increasing the risk of metastatic development." (PMID 31447859, 2019). "IL-6 trans-signaling results in strong phosphorylated STAT3 expression and a significantly increase tumor-associated antigens carcinoembryonic antigen-related cell adhesion molecule 5/6 (CEACAM5/6) expression." (PMID 28725043, 2017). "Our data show the upregulation of the tumor-associated antigens CEACAM5/6 by trans-signaling of the pro-inflammatory cytokine IL-6." (PMID 26673628, 2015). "One of the most important tumor-associated antigens for CRC is carcinoembryonic antigen-related cell adhesion molecule 5 (CEACAM5), which is involved in cell adhesion, migration, anoikis, tumor invasion and metastasis." (PMID 26673628, 2015). "Targeting the tumor-associated expression and oncogenic functions of CEACAM5, a pile of monoclonal antibodies against CEACAM5 have been developed in previous years to facilitate the diagnosis and therapy of human cancers." (PMID 21731662, 2011). "Conversely, in patients who underwent perioperative chemotherapy, the tumor tissue appeared largely decellularized and more fibrotic, leading to a considerable loss of CEACAM5 expression, although the difference between the tumor and HM derived from the same patients was still significant." (PMID 40868067, 2025). "It remains to be investigated whether targeting CEACAM5/6 by CAR T-cells can provide an additional benefit to cancer therapy by acting on the constituents of the immunosuppressive elements of the tumor-associated microenvironment." (PMID 38279989, 2024). "Tusamitamab ravtansine (SAR408701) is a targeted ADC against tumor cells expressing CEACAM5, composed of a humanized anti-CEACAM5 monoclonal antibody covalently linked to the potent cytotoxic agent, maytansinoid DM4, via a cleavable linker." (PMID 38001628, 2023).